MAPK14 (mitogen-activated protein kinase 14)
Diseases named in the same sentence as MAPK14 in open-access papers (continued):
Sharing a sentence is not in itself a finding about the gene and the disease.
cancer (continued). "We then validated MAPK14 downregulation in 344SQP versus 344SQR tumors, and in cancer patients with progression on immunotherapies." (PMID 32973129, 2020). "p38 mitogen-activated protein kinase (MAPK) signaling including p38α MAPK (MAPK14), p38β (MAPK11), p38γ (MAPK12) and p38δ (MAPK13) is associated with the development and progression of several types of cancer." (PMID 32894113, 2020). "The aberrant expression of MAPK14 triggers pro-apoptotic and pro-inflammatory mechanisms in several human diseases including cancers." (PMID 33021963, 2020). "Among them, the DEPs involved in the occurrence and development of cancer are detailed in the protein cluster diagram, including MAPK14, MAPK1 and CCAR2." (PMID 32082999, 2020). "On the other hand, treatment of cancer cell lines with a certain MAPK14 inhibitor has diminished tumorigenic potential in animal models of breast cancer." (PMID 32433496, 2020). "On the other side, ROS-dependent activation of the MAPK14/p38 during starvation is necessary for restraining autophagy activation in cancer cells preserving cell viability in stress conditions." (PMID 31205585, 2019). "The most abundant p38 family member, p38α (also known as MAPK14), has a well-documented, albeit complex role in cancer, exerting cell-type dependent tumor-suppressive or tumor-promoting functions." (PMID 30022044, 2018). "In present study, higher expression of MAPK13 and MAPK14 were correlated with a better prognosis, which led to patients more sensitive to the chemotherapy and prolong the survival time of cancer patients." (PMID 28852147, 2017). "This supports our findings with regards to MAPK14 as a putative target of Metformin, and provides some justification for Metformin’s purported anti-cancer activity." (PMID 26841718, 2016). "MMP9 and MAPK14 might also be related due to MAPK14 and MMP-9 being associated with cancer development." (PMID 38974913, 2024). "MAPK14 has been described either as a cancer inducer or suppressor in different studies." (PMID 37047552, 2023). "MAPK14, also known as p38MAPK, is involved in the initiation of several disease states such as inflammatory disorders, neurodegenerative diseases, cardiovascular diseases, and cancer." (PMID 35740845, 2022). "Increasing evidences suggest that MAPK14 activity may activate the cancer cell migration, invasiveness and angiogenesis." (PMID 34311656, 2021). "Together, combined de-regulation of MAPK14 and ATF2 by loss of miR-622 might be specifically beneficial for cancer cells under stress-inducing conditions including chemotherapy." (PMID 33803354, 2021). "In several cancers, multidrug mechanisms involve activation of MAPK14." (PMID 33021963, 2020). "This suggests that MAPK14–MAPKAPK2 activation plays a role during oxPt response in cancer cells." (PMID 27526785, 2016). "In addition, the recent studies have provided strong evidence that the MAPK14/p38 signaling is involved in cancer cell resistance to chemotherapy treatment." (PMID 24113172, 2013). "Moreover, MAPK14 (p38α) T180/Y182 phosphorylation, which is induced by stress signals, is significantly reduced in primary tumor compared to normal tissue in 2 out of the three cancers tested." (PMID 35501462, 2022). "MAPK14 activation could be a common response of most cancer cells." (PMID 31905767, 2019). "A significantly positive correlation was found between p38/MAPK14 and ABCG2 in these five carcinomas." (PMID 41541684, 2026). "Collectively, our research indicates that TTN, GDF15, and MAPK14 can serve as prognostic biomarkers in female KIRC patients, offering prospects for enhanced treatment and patient outcomes in these cancers." (PMID 40854626, 2025). "A key finding was that a single contaminant can impact different cancers via distinct targets; for example, PFOS appears to target JUN in BRCA but MAPK14 in PRAD." (PMID 41246859, 2025).
cancer (continued). "We first elucidated the expression and prognostic value of Mapk14 in CRC and found that Mapk14 mRNA expression was higher in multiple cancers than in normal tissues, including COAD-READ tissues." (PMID 35141222, 2022). "Based on NCBI BioSystems pathway analysis, the results showed that MAPK14, SRC and MAPK1 belonged to senescence and autophagy in cancer." (PMID 36271672, 2022). "Mapk14 was significantly upregulated in five cancer types (namely, COAD, LIHC, PAAD, READ and STAD) and significantly downregulated in eight cancer types (namely, LUAD, LUSC, BLCA, CESC, KICH, OV, PRAD and UCEC)." (PMID 35141222, 2022). "According to the results, MGST1, GPX3, SP1, TXNRD1, MAPK14, and SOD1 presented with CNV gains among various types of cancers." (PMID 34721758, 2021). "Consistently, MAPK14 selective inhibitor, LY2228820 (ralimetinib), has been shown to produce significant tumor growth delay in multiple cancer models, including GBM, and has now entered clinical trials." (PMID 33021050, 2020). "The transcription levels of MAPK14 and CDC25B in 72 pairs of ccRCC and adjacent healthy tissues from the cancer genome atlas database and the protein expression levels in 66 pairs of clinical samples were analyzed in this study." (PMID 31856414, 2020). "We focused our validation experiments on three major kinases involved in cancer: the tyrosine kinase ABL1, the mitogen‐activated protein kinase (MAPK) member ERK2, and one of the four p38 MAPKs, MAPK14." (PMID 33021050, 2020). "Validation experiments were performed on three major kinases involved in cancer biology: ABL1, MAPK1/ERK2, and MAPK14/p38α." (PMID 33021050, 2020). "Phosphorylation of FOXO3 on Ser7 by the MAPK14 MAP kinase has been shown to promote its nuclear localization in response to doxorubicin, an anti-cancer drug that induces cytotoxicity by stimulating the production of intracellular free radicals." (PMID 27532863, 2016). "The new identified targets for cancer therapy in future using luteolin can be CDK2, CDK6, HGFR, MAPK14, FGF." (PMID 26385094, 2015). "Inhibition of p38 MAPK with a specific inhibitor SB202190 that targets both MAPK11 and MAPK14 resulted in decreased cell viability in all never smoker cancer cell lines to different degrees." (PMID 37686122, 2023). "MAPK14 and STAT3 play a carcinogenic role in the research mechanism of cancer cells." (PMID 36532716, 2022). "The anti-cancer effect of THSWD might by achieved via the down-regulation of MAPK1, HRAS, GRB2, AKT1, and MAPK14." (PMID 34513708, 2021). "The typical cellular localization patterns of MAPK14 and ATF2 were also confirmed in non-HCC cancer cells." (PMID 33803354, 2021).
tumor (138 papers, 2007 to 2025). "The p38 kinase, encoded by MAPK14, has been identified as a central negative regulator of the effective anti-tumor phenotype characteristics of CD8+ T cells." (PMID 39342365, 2024). "Further analyses based on the TIMER method were performed to assess the correlation between Mapk14 and tumor immune infiltration, immune checkpoints, tumor mutational load and microsatellite instability." (PMID 35141222, 2022). "Alternatively, deletion and silencing of several genes of interest, Mapk14, Hopx, and Spink5, have been associated with several tumor types, as well." (PMID 25474466, 2014). "Therefore, we determined the association between genetic alterations in Mapk14 and clinical events (e.g., clinical stage, M-stage, and immunotherapy response) by multi-omic profiling, using large multi-omic data from the same tumor." (PMID 35141222, 2022). "Therefore, we investigated the association between Mapk14 expression and clinicopathological and tumor-infiltrating immune cells." (PMID 35141222, 2022). "Moreover, high expression levels of MAPK14 or ATF2 were associated with advanced tumor stages and a more de-differentiated histological grading." (PMID 33803354, 2021). "However, ablation of MAPK14 in the epithelial cells of the digestive tract of another mouse strain caused development of significantly more tumours." (PMID 26373535, 2015). "Because PI3K/Akt and MAPK pathways are often aberrantly activated in tumor cells, and they are reported to be associated with Cdc42 and huntingtin, thus we performed qRT-PCR to determine the mRNA expression of Akt and MAPK14 (encoding p38 MAPK) in Trip10-overexpressed CP70 and IMR-32 cells." (PMID 21299869, 2011). "MAPK14 (p38 alpha) is a key MAPK family member involved in tumor biology, regulating survival, proliferation, metastasis, and therapy response, as well as stress and inflammation signaling." (PMID 41024254, 2025). "The levels of genes associated with tumor metastasis, including MAPK1, MAPK14, COL5A1, FN1, EP300, and FOSL2, were significantly downregulated after SH intervention." (PMID 41444284, 2025). "Based on previous pharmacological network results, the potential involvement of MAPK14 in the anti-tumor effect of dauriporphine and the regulatory effect of miR-424-5p was raised." (PMID 40500789, 2025). "It has been reported that MAPK14 served as the regulator for the expression and activity of ubiquitinase or deubiquitinase to exert its effects in the tumor’s behavior." (PMID 40918133, 2025). "Early studies have shown that the tumor p38-alpha isoform (p38α, MAPK14) contributes to the dissemination of TNBC by mediating tumor-intrinsic capacities that drive invasion and angiogenesis." (PMID 41282257, 2025). "Inhibiting Mapk14 is an effective method to promote the functional phenotype differentiation of T cells and enhance the anti-tumor effect of engineered T cells in mice." (PMID 39342365, 2024). "In the PPI results, we observed that molecules such as MAPK14, ATP6V1, Itgbs, MB2, STAT3, PKM, ACSS3, and MYL9, which are associated with signal transduction, inflammation, and tumor invasion, exhibited more active interactions with other molecules." (PMID 38203782, 2024). "We found that MAPK14 was highly expressed in 5 of 24 tumor tissues (STAD, CHOL, ESCA, HNSC and LIHC), and ERBB3 is highly expressed in 10 of 24 tumor tissues including STAD." (PMID 37537191, 2023). "In parallel, MAPK14 is involved in tumor-related processes such as cell metabolism, invasion, inflammation and angiogenesis." (PMID 36674696, 2023). "We first analyzed the percentage abundance of Mapk14 in CRC with different types of tumor-infiltrating immune cells." (PMID 35141222, 2022).
tumor (continued). "Our results showed that Mapk14 expression is significantly correlated with different cell types and tumor immune cell infiltration according to the scTIME and TIMER databases." (PMID 35141222, 2022). "Further immunohistochemical analysis of Mapk14 expression at different clinical stages and M stages showed that Mapk14 was significantly highly expressed in tumor tissues, which further suggests the potential use of Mapk14 as a marker of CRC progression." (PMID 35141222, 2022). "Then, we investigated the correlation between Mapk14 expression and tumor-infiltrating immune cells by establishing immune cell scoring heat maps, and the results showed that high Mapk14 expression was significantly associated with immune infiltration in CRC." (PMID 35141222, 2022). "This study demonstrates that Mapk14 is a prognostic biomarker for the clinicopathological features and tumor immune microenvironment of CRC and has potential as a predictive biomarker and immunotherapy target." (PMID 35141222, 2022). "MAPK14/p38 can block the development of neutrophils via autophagy induction and impair inhibition of tumor development." (PMID 36497321, 2022). "Single-cell sequencing of Mapk14 in the tumor immune microenvironment (TIME) was analyzed using the GSE108989 dataset." (PMID 35141222, 2022). "Taken together, these results showed that Mapk14 expression was significantly correlated with tumor immune infiltration." (PMID 35141222, 2022). "MiRNA 421 was reported to suppress a serine/threonine kinase, MAPK14, which regulates apoptosis and cell cycle, ultimately suppressing cellular proliferation and tumor formation." (PMID 34582677, 2021). "BMP7 secreted by tumor cells acts on macrophages and CD4+ T cells in the tumor microenvironment, inhibiting MAPK14 expression and impairing pro-inflammatory responses." (PMID 32973129, 2020). "Our study demonstrates that MAPK14 protein expression is significantly upregulated in sorafenib-resistant HCC tumor samples, but, MAPK14 mRNA levels are normal." (PMID 33021963, 2020). "This 75–90% knockdown of MAPK14 expression resulted in a significant decrease in tumor spheroid growth in vitro." (PMID 33021050, 2020). "Our findings thus demonstrate that miR-216a-3p enhances sorafenib sensitivity in HCC cells and tumor tissues by decreasing MAPK14 levels, thereby inhibiting the MAPK14-dependent MEK/ERK and ATF2 signaling." (PMID 33021963, 2020). "As a future perspective, we can deepen the role of miRNAs in the mentioned network and assess the contribution of the selected miRNAs and their targets in the MAPK14-mediated breast carcinogenesis." (PMID 32433496, 2020). "The results showed that blockade of MAPK14 expression in the mice significantly reduced tumor formation in the pituitary gland, and thus PRL production and secretion in estradiol-induced and DRD2−/− prolactinoma." (PMID 32894113, 2020). "These are examples to show that if the mutant peptides derived from MAPK14 or eEF2 are used as neoantigen targets to stimulate the body, the specific immune response will likely benefit the destruction of tumor cells." (PMID 32241270, 2020). "Our findings show that BMP7 regulates proinflammatory responses in the tumor microenvironment by suppressing mitogen-activated protein kinase 14 (MAPK14) signaling in macrophages and CD4+ T cells." (PMID 32973129, 2020). "In summary, the present study elucidates the role of MAPK14 in promoting tumor growth, and the production and secretion of PRL through in vitro and in vivo experiments." (PMID 32894113, 2020). "Knockout of MAPK14 significantly inhibited tumor overgrowth, and PRL expression was decreased in estradiol-induced mice." (PMID 32894113, 2020). "In our study, the use of RNA interference revealed that MAPK14 expression is crucial to GBM tumor growth in a spheroid model, confirming the therapeutic potential of targeting MAPK14 in GBM." (PMID 33021050, 2020).
tumor (continued). "MAPK14 can act as a tumor suppressor by regulating cell cycle progression and induction of apoptosis or as an oncogene by promoting invasion, inflammation, and angiogenesis." (PMID 32973129, 2020). "Using qRT-PCR and IHC, we found that the mRNA and protein expression levels of MAPK14 in HCC tumour tissues were significantly lower than those in the paired non-tumorous tissues." (PMID 30795787, 2019). "MAPK14 is an important apoptotic inducer, TNF-α, TGF-β and oxidative stress activate MAPK14 signaling pathway to induce apoptosis, and exert its anti-tumor effect." (PMID 31905767, 2019). "We also evaluated regorafenib in combination with the MEK inhibitor refametinib since MEK activation by MAPK14 was proposed to be involved in tumor resistance to sorafenib." (PMID 26599335, 2015). "Further, our results suggest that CRN5 affects tumour-related cell functions on several levels, directly on the actin cytoskeleton and more indirectly via modulation of the MAPK14 and PRMT5 signalling pathways." (PMID 26373535, 2015). "Human lung tumors show reduced expression levels of MAPK14, and tumor abundance, formation, and progression are all increased in Mapk14-null mice expressing oncogenic Kras." (PMID 25474466, 2014). "In animal model, MAP kinase14Δ/ΔKrasG12V mice with extensive lung stem cell numbers and tumor progression have demonstrated decreased C/EBPα expression in vivo, suggesting that C/EBPα is a possible downstream target of MAPK14 (p38α) in the lung." (PMID 23437297, 2013). "In another study, the K-RasG12V-induced tumor model intercrossed with MAPK14Δ/Δ mice (MAPK14 deletion in adult) demonstrated high tumor frequency with low expression of C/EBPα and FoxA2 in the lung." (PMID 23437297, 2013). "Moreover, there were significantly differential expression of MAPK14 between Grade2 STAD tumor tissues and normal sample, and between Grade1 and Grade 3 STAD tumor tissues." (PMID 37537191, 2023). "In addition, we downloaded tumor cell line data from the CCLE database to analyze Mapk14 expression." (PMID 35141222, 2022). "In CRC, Mapk14 is highly expressed in a variety of tumor cell lines." (PMID 35141222, 2022). "GYP significantly reduced the expression of STAT3, EGFR, TYMS and MAPK14 in tumor tissues, while cisplatin combined with GYP could further reduce the expression of STAT3, TYMS and MAPK14 in tumor tissues." (PMID 36532716, 2022). "However, several studies have also demonstrated the protumorigenic activities of MAPK14, which facilitates the survival and proliferation of tumor cells." (PMID 33021050, 2020). "Compared with the estradiol-injected mice, the plasma PRL levels of peripheral blood (P < 0.01) and PRL mRNA expression levels in the pituitary gland (P < 0.05) were decreased, and the tumor/body weight ratio (P < 0.001) was significantly decreased in the estradiol-injected MAPK14−/− mice." (PMID 32894113, 2020). "Furthermore, miR-216a-3p OE in HCC cells promotes sorafenib sensitivity in the xenograft tumor nude mice model by downregulating MAPK14 protein levels and inhibiting activation of MEK/ERK and ATF signaling pathways." (PMID 33021963, 2020). "The MAPK14/p38α signaling pathway has been classically considered a tumor suppressor." (PMID 33021050, 2020). "MAPK14, a well-known tumour suppressor of HCC, displayed two binding sites for miR-421." (PMID 30795787, 2019). "However, while overexpression of miR-200a expression decreases p38α/MAPK14 protein in ovarian adenocarcinomas and promotes tumorigenesis, it enhances tumor cell death and slows tumor growth under treatment with paclitaxel (Taxane family group)." (PMID 29270905, 2017). "In the present study, we demonstrate that the expression level of CRN5 is associated with the malignant progression of colon carcinoma, and that CRN5 over-expression led to elevated tumour cell migration velocity as well as altered MAPK14 and PRMT5 signalling pathways." (PMID 26373535, 2015).